CCL5 (C-C motif chemokine ligand 5)
Diseases named in the same sentence as CCL5 in open-access papers (continued):
Sharing a sentence is not in itself a finding about the gene and the disease.
tumor (continued). "Overall, the described involvement of the CCR5 ligands CCL5 and CCL3 in CRC-driven immune escape mechanisms and their tumor-promoting properties seemed to outweigh the capacity of CCL4 to trigger the recruitment of peripheral effector T cells in CRC metastases via CCR5 engagement." (PMID 36428508, 2022). "In human solid tumors, CCL5 expressed by tumor cells and CXCL9 expressed by both macrophages and DCs are important for tumor infiltration by T cells, a process that also involves the identification of tumor antigens by T cells." (PMID 36387070, 2022). "In our recent work, we hypothesized that the interaction at the TNBC tumor boundary between adipose stem cells (ASCs) and local fibroblasts (MDA-MB-231 cells) produces high levels of CCL5." (PMID 36430633, 2022). "Therefore, we proposed that malignant TCyEM cells appeared to produce high levels of CCL5 and CCL4 to recruit and polarize CD163-expressing M2 TAMs, forming a tumor-supporting environment in TCyEM cases." (PMID 35241665, 2022). "Besides, M2-TAMs-mediated CCL2, CCL3, CCL4, CCL5 or CCL20 release also promotes the recruitment of Treg cells into TME, which further suppresses the anti-tumor functions of T cells and NK cells." (PMID 36419877, 2022). "Interestingly, some reports have proven that patrolling monocytes can recruit large numbers of NK cells to tumor sites, especially metastatic tumor lesions, through the release of cytokines, such as CCL3, CCL4, and CCL5 47-49." (PMID 36438484, 2022). "Additionally, there was a significant correlation between CCL5 and TNF α levels in the tumor (r = 0.76 p < 0.0001) and the margin (r = 0.92, p < 0.0001) tissue." (PMID 35208526, 2022). "Doubly mutant PCa tissues for the Phosphatase and tensin homolog (Pten) and ERK5 exhibited a significant upregulation of lymphocyte-recruiting chemokines (Ccl5 and Cxcl10), as well as an increase in CD4+ T-cell infiltrate in the tumor stroma upon ERK5 ablation." (PMID 35053510, 2022). "Tumor-infiltrating MDSCs could also recruit CCR5+ Tregs to the tumor site through releasing CCR5 ligands CCL3, CCL4, and CCL5 to promote tumor growth in a B16 melanoma model." (PMID 35267547, 2022). "Additionally, these cells showed reduced levels of Ccl5, which together with XCL1, attracts XCR1+ conventional dendritic cells 1 (cDC1) into the TME, thereby promoting tumor control." (PMID 36372017, 2022). "The authors found that the co-expression of CCL5 and CXCL9 could promote CD8+ T cells infiltration, prolong survival, and alleviate reactivity to PD-1 inhibitors in tumor tissue." (PMID 35892835, 2022). "However, CCL5−/−MDSC-DCs, particular in the present of ATRA, had dramatically tumor-inhibitory effects on both 4T1 and MC38 tumor-bearing models (Fig. 2BandC)." (PMID 35707772, 2022). "In addition, autophagy blocks CTL-mediated and NK-cell-mediated tumor killing and inhibits chemokine CCL5 expression, which is required for recruitment of NK-cell migration to the TIME and ultimately results in immune escape in tumor cells." (PMID 36229854, 2022). "Expression level and release of the cytokine CCL5 were increased by inhibition of BECN1 via the MAPK8/JNK-JUN/c-Jun signaling pathway, resulting in tumor growth inhibition and massive natural killer cell infiltration into the tumor microenvironment." (PMID 35761331, 2022). "Many cytokines secreted by tumor cells can recruit macrophages to the TME, but some of them are exclusively produced by CSCs: CCL2, CCL3, CCL5, CXC motif chemokine ligand 12 (CXCL12), olfactomedin-like 3 (OLFML3), stromal-cell-derived factor-1b (Sdf1b), IL-6, IL-33, and CSF-1." (PMID 35740975, 2022). "Notably, cytokines such as CCL2, CCL5, and CSF1 were found to be involved in the attraction of MDSCs to the tumor site." (PMID 36430577, 2022).
tumor (continued). "The homeoprotein Six1, a member of the Six family of homeodomain transcription factors, increases the expression of CCL2, CCL5, and vascular endothelial growth factor (VEGF), attracts macrophage infiltration into the tumor, and further leads to CRC tumor growth, progression, and metastasis." (PMID 35935996, 2022). "On the other hand, it has been demonstrated that targeted inhibition of the autocrine CCL5/CCR5 axis could reprogram immunosuppressive myeloid cells and suppress tumor progression." (PMID 36430701, 2022). "This implies that SASP is sufficient to sensitize tumor cells to ICB and, in agreement, injection of SASP-activated tumor cells sensitizes an immunologically cold murine ovarian model to ICB, whereas CCL5 suppression in another model attenuates T cell inflammation." (PMID 35082152, 2022). "Additionally, NK cells directly attract cDC1 accumulation inside the tumor lesion by XCL1 and CCL5 chemokines and promote their differentiation under the release of Flt3 factor with a strong inhibition of this axis induced by PGE2 tumor secretion." (PMID 36230990, 2022). "Additionally, tumor cells secrete various chemokines such as SDF-1, CCL2, CCL5, and adiponectin which mediate the homing of endothelial progenitor cells into tumor neovasculature." (PMID 36091174, 2022). "Due to their unstable genomes, these cells produce particular cytoplasmic DNA fragments (at baseline or under chemotherapeutic treatments) which sense the cGAS/STING and type I IFN signaling pathways to induce the production of CXCL10 and CCL5 and the recruitment of CD8 T cells at the tumor site." (PMID 36429101, 2022). "Tumor cells themselves as well as stromal cells can produce chemotactic molecules involved in monocyte recruitment at the tumor site, such as CC chemokine ligand 2 (CCL2) and CCL5, as well as growth factors such as vascular endothelial growth factor (VEGF) and M-CSF." (PMID 36359283, 2022). "By migrating to the tumor, MDSC elevates Arg1 and iNOS, downregulating ROS production, upregulating PD-L1 on MDSC surface, and producing CCL4 and CCL5 chemokines to attract T-regs, strongly suppressing the activity of CTLs and NK cells in the tumor microenvironment." (PMID 35214123, 2022). "Studies have shown that CD4+ T cells may activate STAT3 through CCL5 to affect the chemosensitivity of PCa, and the expression of MHC I increases the immunogenicity of PCa tumor cells." (PMID 34215720, 2021). "CCL4 and CCL5 also mediated CD8+ and γδ T cell responses, which enhanced anti-tumor immunity." (PMID 34503058, 2021). "Intriguingly, we found that the circIGF2BP3/PKP3 axis could also decrease the level of CCL5 in the TME, thus contributing to decreased CD8+ T cell recruitment into tumor regions." (PMID 34416901, 2021). "Additionally, some other chemokines controlling T lymphocyte homing to peripheral tissues, such as CCL5, CXCL9, CXCL10, and CXCL11, were also highly expressed in tumours containing large numbers of tumour HEVs." (PMID 33917287, 2021). "Similarly, CCL5 binds its receptor CCR5 with high affinity and promotes tumor progression through the CCL5/CCR5 signaling axis." (PMID 34777462, 2021). "Our findings are in accordance with the previous statements, as we found that both ADMSC and mature adipocytes secrete factors that could contribute to tumor development like IL6, EGF, PTGS2 and IL4 in ADMSC, and CCL5, IL1β and IGF in adipocytes." (PMID 33801973, 2021). "CCL5 and the other MEKK1-dependent chemokines are ligands for the GPCR CCR5, and we show that the CCR5 antagonist Maraviroc strongly inhibits fibroblast-induced tumor cell migration." (PMID 33868996, 2021).
tumor (continued). "Factors that can promote the anti-tumor neutrophil phenotype include chemokines (e.g., CXCL2, CXCL5, CXCL8, CCL2, CCL3, CCL5, CXCL12 (SDF-1), CXCL16 and IL-8) alone or together with G-CSF/GM-CSF, TNFα, IFNβ, IFNγ, IFNγ together with TNFα, Resolvin D1, hepatocyte growth factor (HGF) and IL-17." (PMID 34572138, 2021). "In the present study, the expression levels of CCL5, CXCR6 and CD3E exhibited a high correlation with the infiltration levels of CD8+ T cells, and the expression levels in HCC samples were lower than those that in adjacent non-tumor samples." (PMID 34218795, 2021). "In addition, they secrete chemoattractants such as CCL5, CXCL1, CXCL5, CXCL7 and CXCL8 and CXCL12, which induce migration of tumor cells to metastatic lesions." (PMID 34112253, 2021). "In squamous cell carcinoma, nuclear focal adhesion kinase (FAK) regulates transcription of CCL5 to promote T regulatory cell recruitment and exhaustion of CD8+ T cells to promote tumor growth, and treatment with FAK inhibitors reactivates anti-tumor immune responses." (PMID 33807608, 2021). "Expression levels of Ccl2 and Ccl5 were not significantly altered between tumours and corresponding liver tissues from Ccne1f/f and Ccne1−/− animals." (PMID 34830835, 2021). "This microRNA was shown to indirectly regulate the expression of several cytokines (IL-5, IL-6, CCL-5, TNF-alpha) that in turn may alter the immune infiltration in the tumor microenvironment." (PMID 33544339, 2021). "Furthermore, it was reported that tumor-derived osteopontin (OPN), a multipotent chemoattractant, promotes the expression of CCL5 in MSCs, which leads to incremented metastasis." (PMID 33472580, 2021). "and CCL5 when compared to isotype-treated tumours, but had no impact on CXCR3 expression by T cell subsets." (PMID 33925140, 2021). "Furthermore, the results of tissue samples have demonstrated that both CCL5 and CCL20 were markedly upregulated in HCC tumor tissues than in adjacent tissues." (PMID 34938730, 2021). "CCL5, also known as RANTES, was reported to be produced by cancer cells or nonmalignant stromal cells in the tumor microenvironment." (PMID 34899325, 2021). "CAF with tumor-promoting functions secrete growth factors (HGF, IGF1, CTGF, PDGF, VEGF, LIF), cytokines (IL-1, IL-4, IL-6, IL-8, IL-10, TGF-β), and chemokines (CCL2, CCL5, CXCL5, CXCL9, CXCL10, CXCL12), WNT5α, and bone morphogenic protein 4 (BMP4), which promote tumor progression." (PMID 35008832, 2021). "There are several possible reasons why activation by CCL5-stimulated EVs rather than direct CCL5 interaction is required to educate tumor-recruited macrophages." (PMID 34298673, 2021). "NK cells ́ critical functions to induce an effective tumor immunity depend on a successful crosstalk with conventional dendritic cells (cDC1) and the production of the chemokines CCL5 and XCL1, and that tumor-derived prostaglandin E2 (PGE2) interferes with this reciprocal stimulatory loop." (PMID 34394116, 2021). "Indeed, these studies suggest that the major monocyte recruiting pathways (M-CSF/CSF-1R, CCL2/CCR2, CCL3/CCR1, CCL3/CCR5, CCL5/CCR5 and CX3CL1/CX3CR1) enable tumor survival by supplying the TME with pro-tumorigenic TAMs." (PMID 34988021, 2021). "In response to interferons, macrophages are polarized and activated into pro-inflammatory classical M1 type that produces cytokines, such as interferon-γ (IFN-γ), tumor necrosis factor-α (TNF-α), IL-23, IL-12, CCL5, CXCL9, CXCL10, and CXCL5 and help destroy tumor cells via activating Th1 cells." (PMID 33925575, 2021). "The anti-tumor “N1” phenotype exhibited increased tumor cytotoxicity, elevated expression of CXCL13, CCL3, CCL6, CXCL10, TNFα and ICAM-1 and low ARG1 content, while the pro-tumor “N2” neutrophils expressed high levels of ARG1, MMP9, VEGF and several cytokines, including CCL2, CCL5, CCL17 and CXCL4." (PMID 34572138, 2021).
tumor (continued). "Our previous study showed that CCL5 mediates macrophage recruitment to TNBCs, and the metastasis suppressor Raf Kinase Inhibitory Protein (RKIP) blocks this recruitment by inhibiting CCL5 expression in tumor cells and CCR5 expression in macrophages." (PMID 34298673, 2021). "Weak effector T cell responses in therapy-treated DIO mice were accompanied by low intratumoral concentrations of the T cell chemoattractant CCL5, heightened concentrations of pro-tumorigenic GM-CSF, and impaired proliferative capacity of CD44+CD8+ T cells in tumor-draining lymph nodes." (PMID 34064933, 2021). "Moreover, our in vivo study demonstrated that tumor growth and metastatic potential of Hepa1–6 cells was significantly repressed by MAX or CCL5 depletion in immune-competent mice in comparison to that of the vector control." (PMID 34215748, 2021). "Next, ELISA analyses showed that HIF‐1α MOCK fibroblasts secreted more CCL5 than HIF‐1α KO fibroblasts, indicating that CCL5 might be the main factor in the tumour promoting effect of HIF‐1α MOCK fibroblasts." (PMID 33943003, 2021). "Upregulated within the tumor-infiltrating CD4+ T cells were heat shock proteins (HSPA1A and HSPA1B), Jun and FOS constituents (FOS, JUN, and JUNB), MHC-II molecules (HLA-DRB), and secreted molecules (CCL5, GZMA, and GZMK)." (PMID 33504936, 2021). "Therefore, we suggest that MVC, by reducing the binding of CCL5 to CCR5, is able to inhibit TAM promotion of tumour cell proliferation, invasion and metastasis." (PMID 34638423, 2021). "Furthermore, it is documented that tumor cells with DDR shortage show constitutive triggering of cellular IFN responses and emission of TIL conscripting chemokines, CCL5 and CXCL10." (PMID 34152511, 2021). "Thus, although the focus of this work was on studying anti-tumour CAR-T cell responses, simultaneous activation of NK cells is also likely given that both CCL5 and IL-15 are key drivers of NK cell recruitment and activation." (PMID 34888493, 2021). "EPCs are recruited into ischemic or hypoxic tumours predominantly in response to chemokines (e.g., CXCL12, CCL2, CCL5) and growth factors (e.g., VEGF, bFGF), which interact with their respective receptors (e.g., CXCR4, CCR2, CCR5, VEGFR2) on the surface of EPCs." (PMID 34035882, 2021). "Interestingly oncolytic adenovirus armed with CCL5 and IL-15 enhanced CAR-T recruitment to tumour sites and cytotoxicity in an in vivo model of neuroblastoma." (PMID 34888493, 2021). "Triple-negative breast cancer (TNBC) 4T1 cell line grew less in Ccl5-null animals because of increased tumor-infiltrating cytotoxic CD8 T cells and decreased Treg cells in tumor-draining lymph nodes." (PMID 34572013, 2021). "HCC with down-regulated IGF1R led to an increase of C-C motif chemokine ligand 5 (CCL5) secretion, which may function as a chemotactic factor for immune cell in a tumor microenvironment." (PMID 33803804, 2021). "Hypoxic tumor cells around dying tumor cells in the TC can also produce various kinds of cytokines regulated by HIF, such as C–C chemokine ligand type 5 (CCL5), CXCL12, vascular endothelial growth factor A (VEGF-A), endothelin (ET)-1, ET-2 and semaphorin-3A (Sema3A)." (PMID 34172088, 2021). "Although CCL2 expression in the entire cancer tissues was slightly increased overall compared with that of the normal tissues, CCL2 and CCL5 expression were not related to p16INK4A positive tumor cells." (PMID 33643790, 2021). "In addition, TCGA dataset analysis also showed a higher positive correlation coefficient between CCL5 and FOXP3 expression in HCC with tumor recurrence compared to cases with good prognosis (r = 0.49 vs 0.13)." (PMID 34215748, 2021). "In addition, analysis of two published datasets provided evidence that the expression of CCL5 was positively correlated with Tregs (FOXP3) in HCC tumor tissues and PoV tumor thrombus." (PMID 34215748, 2021).
tumor (continued). "On one hand, CCL5 could promote CSCs self‐renewal and recruit the immunosuppressive cells (such as CCR5+ TAMs and Tregs) to form a tumor‐protecting TME." (PMID 33463063, 2021). "While neither intratumoral CCL5 nor anti-PD-L1 (atezolizumab) alone inhibited tumor growth, CCL5 in combination with anti-PD-L1 significantly reduced tumor growth relative to all individual arms (p < 0.05)." (PMID 34030676, 2021). "Additionally, tumors secrete CCL5 which recruits Tregsvia CCR5 and pre-clinical studies with CCR5 inhibitors have decreased Treg tumor infiltration and tumor growth." (PMID 34177968, 2021). "Therefore, we also examined the correlation between tumor tissue PD-L1 expression and serum IRGPI, as well as the serum levels of CCL5 or CCL25." (PMID 34771505, 2021). "This may be partly due to other tumor-derived factors also attract circulating monocytes to the tumor site and differentiate into TAMs, such as CSF1, CCL5, CXCL12 and CX3CL1." (PMID 33564072, 2021). "Compared with TC-1 without irradiation, TC-1 tumor cells pretreated with irradiation were induced greater production of CCL5 and CXCL10 by IFN-γ." (PMID 33469123, 2021). "Tumor-conditioned monocytes demonstrated an increase in in vitro migration in response to CCL5 and CXCL12 when compared to non-conditioned monocytes." (PMID 34975843, 2021). "Moreover, examination of cytokine/chemokine production in the tumor microenvironment revealed an increase in the levels of chemoattractive cytokines such as CCL3, CCL4, CCL5, CXCL9, CXCL10 and CXCL11." (PMID 32033490, 2020). "CCL5 and VCAM1 have been shown to promote tumor progression and metastasis in ESCC." (PMID 33323552, 2020). "However, the combination of CCL5 overexpression and LCMV treatment was highly effective in restricting the tumor and increasing survival of mice." (PMID 32973762, 2020). "Differential expression analysis of pre- and post-treatment tumor-infiltrating MAIT cells revealed upregulation of the activation marker HLA-DRB1, the cytotoxic effector GZMH, and the chemokines CCL4 and CCL5 following anti-PD-1 therapy in both types of cancer." (PMID 32849590, 2020). "Tumor-infiltrating NK cells differentiate into two main populations with distinct profiles of chemokine gene expression: XCL1+XCL2+ NK cells and CCL3+CCL4+CCL4L2+CCL5+ NK cells." (PMID 33424862, 2020). "A possible explanation behind the positive effect of eosinophils is their capacity to recruit cytotoxic T lymphocytes through CCL5, CXCL9, and CXCL10, to induce an anti-tumor phenotype in macrophages through TNFα and IFNγ and to normalize the tumor vasculature." (PMID 32793228, 2020). "IHC staining showed decreased expression of EZH2, CCL5, and MMP2 in tumor tissues." (PMID 31855281, 2020). "Tumor associated macrophages (TAMs) and myeloid suppressor cells (MDSCs) release chemokines, such as CCL17, CCL22, CCL5, CCL6 or CCL28, depending on the tumor type, to attract Tregs expressing the chemokine receptors CCR4, CCR5, CCR10 and CXCR3 from secondary lymphoid tissues to the tumor." (PMID 32937953, 2020). "First, it describes the involvement of the CCL5/CCR5 axis in cancer progression, including autocrine and paracrine tumor growth, ECM (extracellular matrix) remodeling and migration, cancer stem cell expansion, DNA damage repair, metabolic reprogramming, and angiogenesis." (PMID 32630699, 2020). "qPCR results showed that levels of chemokines (CXCL10, CCL5, IFN-β) were increased after silencing of TAZ in CALU-3, NCI-H520, and M109 at the presence of STING pathway agonist cGAMP and in SKIL-silenced NSCLC cell-derived tumor blocks." (PMID 33268765, 2020). "This calculation revealed supra-additive upregulation of many of the same cytokines/chemokines in LKB1-reconstituted tumor spheroids co-cultured with MVNs, including CCL2 and CXCL10, while there were some differences such as IL-6, which was amplified, and CCL5, which was suppressed." (PMID 33013881, 2020).